CPNE7 (copine 7)
Description:
Calcium-dependent phospholipid-binding protein that may play a role in calcium-mediated intracellular processes.
Tractability: Antibody: UniProt places it where antibodies can reach, with high confidence; its Gene Ontology location is reachable by antibodies, with high confidence. PROTAC: ubiquitination databases record sites on it; its protein half-life has been measured.
Gene: Protein-coding gene on chromosome 16 (89,575,732 to 89,597,247, forward strand). Ensembl gene ENSG00000178773.
Subcellular location: Cytoplasm; Nucleus; Cell membrane
Pathways (Reactome):
Metabolism: Glycerophospholipid biosynthesis
Gene Ontology:
Molecular function: protein binding; protein-membrane adaptor activity; calcium-dependent phospholipid binding
Biological process: cellular response to calcium ion; glycerophospholipid biosynthetic process; lipid metabolic process
Cellular component: cytoplasm; extracellular exosome; nucleus; plasma membrane; synapse
Genetic constraint (gnomAD): Loss-of-function variants: 78 observed, 61.88 expected, observed/expected ratio (o/e) 1.26, 90% interval 1.05 to 1.52. The synonymous counts are far from expectation, so gnomAD's model fits this gene poorly and the ratio says little. Missense variants: 1,012 observed, 718.37 expected, observed/expected ratio (o/e) 1.41, 90% interval 1.34 to 1.48. Synonymous variants: 468 observed, 311.78 expected, observed/expected ratio (o/e) 1.5, 90% interval 1.39 to 1.62.
Homologues: Orthologues: macaque CPNE7 (97% identical), mouse Cpne7 (89% identical), rat Cpne7 (89% identical), guinea pig CPNE7 (85% identical), dog CPNE7 (82% identical), chimpanzee CPNE7 (77% identical), tropical clawed frog cpne7 (76% identical), zebrafish cpne7 (74% identical), Caenorhabditis elegans nra-1 (41% identical), Caenorhabditis elegans cpna-2 (40% identical), Caenorhabditis elegans gem-4 (40% identical), Caenorhabditis elegans cpna-4 (26% identical). Paralogues in human: CPNE4 (69% identical), CPNE6 (65% identical), CPNE3 (54% identical), CPNE2 (52% identical), CPNE1 (50% identical), CPNE8 (50% identical), CPNE5 (49% identical), CPNE9 (47% identical).